BLACAT1 (BLACAT1 overlapping LEMD1 locus)
Diseases named in the same sentence as BLACAT1 in open-access papers (continued):
Sharing a sentence is not in itself a finding about the gene and the disease.
cancer (18 papers, 2017 to 2025). A tumor composed of atypical neoplastic, often pleomorphic cells that invade other tissues. "As a newly discovered lncRNA, bladder cancer-associated transcript 1 (BLACAT1) has been reported to correlate with poor clinical outcomes in several different cancers." (PMID 31061820, 2019). "Here, we focused on BLACAT1 and provided a comprehensive pan-cancer analysis to evaluate the diagnostic and prognostic values of BLACAT1." (PMID 29037201, 2017). "The serum BLACAT1 had a high diagnostic performance among these 12 types of cancer." (PMID 29037201, 2017). "Other lncRNAs, such as LOC553103 and BLACAT1, also showed the capacity for pan-cancer detection with AUC values ranging from 0.826 to 0.966 and 0.833 to 0.967 for individual cancer types, respectively." (PMID 36980276, 2023). "BLACAT1, is branded as a new budding star, for a valuable and potential prognostic prediction for cancers." (PMID 36939965, 2023). "Due to its oncogenic potential, lncRNA BLACAT1 is defined as a carcinogenic lncRNA in many kinds of cancers." (PMID 31061820, 2019). "We thoroughly searched PubMed, Embase, and Web of Science databases for eligible studies published until November 11, 2018, in which the relationship between BLACAT1 expression and cancer prognosis was explored." (PMID 31061820, 2019). "Our results further revealed that the level of lncRNA BLACAT1 expression was a valuable and potential prognostic predictor for cancers." (PMID 31061820, 2019). "Herein, a meta-analysis was performed to comprehensively explore the relationship between prognosis and lncRNA BLACAT1 expression in different cancers." (PMID 31061820, 2019). "Recently, many researchers focused on lncRNA BLACAT1 due to its potential role in predicting cancer prognosis." (PMID 31061820, 2019). "Many studies have investigated the functional mechanisms of lncRNA BLACAT1 on tumorigenesis and progression in various cancers." (PMID 31061820, 2019). "In conclusion, our study suggests that high lncRNA BLACAT1 expression is a valuable predictor for poor cancer prognosis in OS, TNM stage, tumor grade, and LNM." (PMID 31061820, 2019). "In our study, we also evaluated the diagnostic accuracy of BLACAT1 among CRC patients, non-cancer patients and health controls." (PMID 28406230, 2017). "The relative AUC of serum BLACAT1 in cancer patients ranged from 0.833 to 0.967 compared to that in healthy subjects." (PMID 29037201, 2017). "The expression level of BLACAT1 both in serum and tissues in multiple cancer types were significantly upregulated compared to those of matched non-cancer participants." (PMID 29037201, 2017). "Meanwhile, the BLACAT1 not only has an obviously diagnostic value for CRC, but it has distinctly differential value to separate CRC from other non-cancer diseases." (PMID 28406230, 2017). "Behind these results, BLACAT1 engrossed a large amount of attention from cancer scientists." (PMID 36939965, 2023). "Moreover, bladder-cancer-associated transcript 1 (BLACAT1) was reported to stimulate the expression of ATG7 by miR-17 and promote autophagy and drug resistance in NSCLC cancer cells." (PMID 35401751, 2022). "Based on previous studies, SAMD12‐AS1 was considered to promote cell proliferation through the interaction with NPM1, while abnormal regulation of BLACAT1 could also promote the proliferation and metastasis of cancer cells." (PMID 33934391, 2021). "Accumulating evidence has proven that lncRNA BLACAT1 is closely related to cancer." (PMID 31061820, 2019). "All these findings indicated that lncRNA BLACAT1 could be a potential predictor of worse clinical outcomes for cancer patients." (PMID 31061820, 2019). "Third, no sufficient data could be used to explore the prognostic value of lncRNA BLACAT1 expression in a specific type of cancer." (PMID 31061820, 2019). "Therefore, lncRNA BLACAT1 is a promising prognostic biomarker for various cancers." (PMID 31061820, 2019).
cancer (continued). "However, the generalized applicability of lncRNA BLACAT1 in predicting prognosis for cancers remains unknown." (PMID 31061820, 2019). "All the findings concluded that lncRNA BLACAT1 might be a promising therapeutic target for cancers." (PMID 31061820, 2019). "Consequently, cancer patients with high lncRNA BLACAT1 expression tend to have a poor prognosis." (PMID 31061820, 2019). "Moreover, BLACAT1 also had distinct value to discriminate CRC from other non-cancer diseases." (PMID 28406230, 2017). "Therefore, lncRNA BLACAT1 may serve as a promising predictor in cancer prognosis." (PMID 31061820, 2019). "The respective sensitivity and specificity were 83.3% and 76.7% for BLACAT1 with the cutoff value of 1.177 between CRC patients and health controls, 56.7% and 92.9% with the cutoff value of 5.035 between CRC patients and non-cancer patients." (PMID 28406230, 2017). "The area under the curve (AUC) were 0.858 (95% CI: 0.765–0.951) for BLACAT1 between CRC patients and health controls, and 0.800 (95% CI: 0.689–0.911) between CRC patients and non-cancer patients." (PMID 28406230, 2017). "Meanwhile, it was also found that BLACAT1 was significantly up-regulated between CRC patients and non-cancer patients." (PMID 28406230, 2017). "The transient resistance of cancer cells to the drug oxaliplatin is the result of drug-induced upregulation of the BLACAT1 lncRNA that, in turn, serves as an inhibitory sponge (ceRNA) of miR-136 leading to elevated expression of ABCB1 and export of the drug from the cancer cells." (PMID 39761690, 2025). "High expression level of LncRNA BLACAT1 was identified to be linked with shorter OS (HR: 2.02, 95% CI: 1.66-2.46, p < 0.001) and PFS (HR: 2.424, 95% CI: 1.827-3.020, p < 0.001) in cancer patients as opposed to low expression levels." (PMID 38601076, 2024). "Namely, high lncRNA BLACAT1 expression may serve as a negative predictor for cancer prognosis." (PMID 31061820, 2019).
tumor (11 papers, 2017 to 2025). "Similarly, the overexpression of lncRNA bladder cancer-associated transcript 1 (BLACAT1) is reported to be associated with tumor malignant features in patients with GBM." (PMID 38204968, 2023). "Meanwhile, this study also demonstrated that high BLACAT1 expression significantly correlated with more advanced TNM stage, higher tumor grade, and higher risk of LNM." (PMID 31061820, 2019). "The real-time PCR result showed that BLACAT1 was up-regulated in tumor tissues compared to adjacent normal tissues." (PMID 30733855, 2019). "In vivo results showed that BLACAT1 interference inhibited tumor formation (all P < 0.05)." (PMID 33072570, 2020). "First, we examined the BLACAT1 level in the CRC tumor tissues." (PMID 28277544, 2017). "LncRNA BLACAT1 predicts poor prognosis and promotes cell proliferation through epigenetically silencing p15 in CRC tumor cells." (PMID 33109776, 2020). "The results showed that the growth rate and weight of tumor decreased significantly, the expression of CDKN1C was increased and CCNE was decreased after silencing BLACAT1, but reversed under up-regulating BLACAT1 treatment." (PMID 33072570, 2020). "It suggested that interference with BLACAT1 can up-regulate CDKN1C expression and inhibit tumor growth in vivo." (PMID 33072570, 2020). "There was significant difference between elevated lncRNA BLACAT1 expression and advanced tumor TNM stage (OR: 2.29, 95% CI: 1.15-4.56, p = 0.005, I2 = 70%, random-effect) and high tumor grade (OR: 1.67, 95% CI: 1.11-2.53, p = 0.01, I2 = 70%, fixed-effect)." (PMID 31061820, 2019). "However, controversies emerged regarding the predictive value of lncRNA BLACAT1 in some prognostic parameters, e.g., TNM stage, tumor grade, and LNM." (PMID 31061820, 2019). "High expression of lncRNA BLACAT1 may predict a poor prognosis in OS, TNM stage, tumor grade, and LNM." (PMID 31061820, 2019). "In conclusion, our results indicated that downregulated plasma BLACAT1 is a potential biomarker for PTC detection, and may predict tumor aggression in patients with PTC." (PMID 29599647, 2018). "Furthermore, correlations of BLACAT1 and clinicopathological traits of PTMC patients (n = 62, tumor volume < 1 cm3) were also analyzed." (PMID 29599647, 2018). "The clinical studies indicated that lack of BLACAT1 was related to tumor size, metastasis." (PMID 30733855, 2019). "Moreover, elevated BLACAT1 expression was significantly associated with advanced TNM stage (OR: 2.29, 95% CI: 1.15-4.56, p = 0.005), high tumor grade (OR: 1.67, 95% CI: 1.11-2.53, p = 0.01), and lymph node metastasis (OR: 2.53, 95% CI: 1.80-3.57, p < 0.00001)." (PMID 31061820, 2019).
infection (1 paper, 2017). The state of being infected such as from the introduction of a foreign agent such as serum, vaccine, antigenic substance or organism. "Thus, the pattern of expression found by in silico analysis for MEG9 and BLACAT1 was confirmed with a significant down regulation at 2 and 6 h post-infection, respectively." (PMID 28611953, 2017).
BLACAT1 also shares sentences with these, for which no sentence is quoted: colon adenocarcinoma (1 paper); endometrial cancer (1); esophageal squamous cell carcinoma (1); medulloblastoma (1); nasopharyngeal carcinoma (1); pancreatic adenocarcinoma (1); T-cell lymphoma (1).